NOL8 (nucleolar protein 8)
Description:
Plays an essential role in the survival of diffuse-type gastric cancer cells. Acts as a nucleolar anchoring protein for DDX47. May be involved in regulation of gene expression at the post-transcriptional level or in ribosome biogenesis in cancer cells.
Synonyms: C9orf34; NOP132; FLJ20736; bA62C3.3; bA62C3.4
Tractability: PROTAC: UniProt records ubiquitination sites on it; ubiquitination databases record sites on it; its protein half-life has been measured.
Gene: Protein-coding gene on chromosome 9 (92,297,358 to 92,325,636, reverse strand). Ensembl gene ENSG00000198000.
Subcellular location: Nucleus, nucleolus
Subcellular location (Human Protein Atlas): Nucleoli; Mitotic chromosome
Gene Ontology:
Molecular function: protein binding; RNA binding; nucleic acid binding
Biological process: protein localization to nucleolus; rRNA processing
Cellular component: nucleolus
Genetic constraint (gnomAD): Loss-of-function variants: 68 observed, 87.76 expected, observed/expected ratio (o/e) 0.77, 90% interval 0.64 to 0.95. The upper end of that interval is the gene's LOEUF score, 0.95, which puts it in group 4 of 6, group 1 being the genes least tolerant of losing a copy. Missense variants: 1,166 observed, 1,266.8 expected, observed/expected ratio (o/e) 0.92, 90% interval 0.88 to 0.97. Synonymous variants: 384 observed, 442.65 expected, observed/expected ratio (o/e) 0.87, 90% interval 0.8 to 0.94.
Homologues: Orthologues: chimpanzee NOL8 (99% identical), macaque NOL8 (94% identical), pig NOL8 (74% identical), rabbit NOL8 (72% identical), dog NOL8 (65% identical), mouse Nol8 (63% identical), rat Nol8 (62% identical), tropical clawed frog nol8 (38% identical), zebrafish nol8 (34% identical), Drosophila melanogaster CG14230 (12% identical), Caenorhabditis elegans K07F5.14 (9% identical).
Diseases named in the same sentence as NOL8 in open-access papers:
NOL8 is named in the same sentence as 3 diseases in open-access papers, as found by Europe PMC text mining. Sharing a sentence is not in itself a finding about the gene and the disease.
NOL8 shares sentences with these, for which no sentence is quoted: cancer (1 paper); migraine (1); tumour diseases (1).